MEN1 (menin 1)
Diseases named in the same sentence as MEN1 in open-access papers (continued):
Sharing a sentence is not in itself a finding about the gene and the disease.
tumor (continued). "Although tumor development in these tissues is dependent upon genetic inactivation of the tumor suppressor Men1, loss of both alleles of this gene is not sufficient to induce these cancers." (PMID 26709830, 2015). "Similarly, the time interval between MEN1 diagnosis and age of the first aggressive tumour was significantly shorter in group A (median 36 months) than in group B (median not reached; P = 0.02)." (PMID 25824098, 2015). "MEN1 is a putative tumor suppressor known to physically interact with NFκB proteins." (PMID 26157642, 2015). "In conclusion, we provide the first evidence that among patients who develop MEN1-related tumours, those bearing the CDKN1B V109G polymorphism have a higher frequency to develop aggressive tumours and hence a more aggressive behaviour, emphasizing the added value of this variant." (PMID 25824098, 2015). "The frequency of the wild-type (T/T 56%) versus the polymorphic alleles (T/G and G/G 44%) among our MEN1 patients was not different from that reported for other types of tumours 15,16." (PMID 25824098, 2015). "Similarly, shorter was the time interval between MEN1 diagnosis and age of the first aggressive tumour (P = 0.02)." (PMID 25824098, 2015). "MEN1-related aggressive tumours or other malignancies were more frequent in participants with the CDKN1B genetic variant (8/24 patients in group A versus 5/31 in group B; 33.3 versus 16.1%), although this test did not result in statistical significance (P = NS)." (PMID 25824098, 2015). "Tumors from patients with MEN1 have been observed to harbor the germ-line mutation together with a somatic LOH involving chromosome 11q13, or point mutations, as expected from Knudson’s model and the proposed role of the MEN1 gene as a tumor suppressor." (PMID 23933118, 2014). "More than 90% of tumors from MEN1 patients have loss of heterozygosity (LOH), and this has generally been taken as evidence that the MEN1 gene acts as a tumor-suppressor gene, consistent with Knudson’s two-hit hypothesis." (PMID 23933118, 2014). "Our findings might provide a potent therapeutic approach for treatment of MEN1-mutant tumours and highlight the importance of β-catenin inhibitors in future individualized treatment strategies for PNETs." (PMID 25517963, 2014). "Several groups have published mouse models of MEN1, which replicate the human syndrome and result in tumour development, most commonly in endocrine pancreas, pituitary, parathyroid and thyroid glands, adrenals, in the gonads in some models, as well as other rarer sites." (PMID 22708734, 2012). "All MEN1 mutated tumours in the current study displayed APC promoter 1A hypermethylation, and a weak but significant correlation (Pearson's correlation 0.322, p = 0.027) was revealed between high APC methylation density and presence of an MEN1 mutation." (PMID 20208994, 2010). "This may be supported by the fact that normal cells from MEN1 patients present an elevated level of chromosome alterations and that MEN1 tumours have more genome aberrations than equivalent tumours from non-MEN1 patients." (PMID 17014705, 2006). "The sporadic form presents with two of the three principal MEN1-related endocrine tumours, while the familial form (more frequent and with an autosomal pattern of inheritance) consists of a MEN1 case with at least one first degree relative showing one of the endocrine characterising tumours." (PMID 17014705, 2006).
tumor (continued). "Nevertheless, the lack of a genotype-phenotype correlation means that neither the localisation nor manifestations of MEN1-associated tumours can be predicted." (PMID 17014705, 2006). "Based on loss of heterozygosity in tumors and Knudson's "two-hit" hypothesis, the MEN1 gene was classified as a tumor suppressor and the gene was isolated in 1997 by positional cloning." (PMID 15691381, 2005). "Sequence analysis of all MEN1 coding exons and flanking intronic sequence, in tumours and matched patient leucocyte DNA, did not reveal mutation(s) in any of the 23 tumours studied." (PMID 10389976, 1999). "Using Men1 f/f-RipCre+ mice, which develop both NF-PanNETs and PitNETs, we investigated whether long-term administration of metformin, a first-line anti-diabetic drug, could suppress tumor development and progression." (PMID 41568565, 2026). "As lungNETs are more frequent in MEN1 than originally thought, but generally have an indolent course with infrequent metastases, active surveillance now seems a viable strategy for small sized tumours, as is also recommended in the European Society of Medical Oncology (ESMO) guidelines." (PMID 39587981, 2025). "Although there is improved understanding of the diagnosis and treatment of MEN1, due to the polymorphism of the MEN1 gene and its lack of genotypic/phenotypic consistency, it is impossible to predict associated tumor types based on the mutated gene, so MEN1 is a challenging disease." (PMID 40421248, 2025). "Interestingly, the MEN1 variant was not seen in either G3 neoplasm, suggesting loss of the mutant MEN1 locus on chromosome 11q in the G3 neoplasms." (PMID 39556303, 2024). "Furthermore, the deactivation of Men1 gene in murine glucagon-secreting alpha cells may result in the development of an insulin-hypersecreting tumor, whereas the deactivation of this gene in insulin-secreting beta-cells may result in glucagonoma." (PMID 39456803, 2024). "Having shown that the MEN1 D418N mutation failed to restore TGFβ signaling, we next investigated whether blocking its degradation could restore TGFβ responses and tumor suppression." (PMID 38891107, 2024). "At the Catalogue of Somatic Mutations in Cancer (COSMIC), only a subset of all the MEN1 germline mutations have been reported as somatic mutations in tumors, suggesting that the mutations likely contribute to clinical pathologies rather than to neoplasia." (PMID 39519139, 2024). "However, this anti-tumor effect of leflunomide could be reversed by increasing the concentration of pyrimidine metabolites, orotate and uridine, indicating that MEN1-/- cells require increased levels of critical pyrimidine intermediates for survival." (PMID 39034953, 2022). "Thus, the identification of specific circulating miRNAs in MEN1 patients could lead to potential tumour biomarkers and possible molecular targets for therapies." (PMID 35900839, 2022). "Thus, longitudinal analysis of miR-3156-5p and MORF4L2 within an individual MEN1 patient could provide important information on when tumour development has occurred and aid in determining the appropriate timing to initiate more invasive screening methods." (PMID 35900839, 2022). "Furthermore, MEN1 is a tumor suppressor and as such could contribute to reported STING roles in DNA damage sensing in cancer." (PMID 34541469, 2021). "When a copy of the wild type MEN1 gene is conserved, it can be speculated that the over-expression of miR-664 leads to silence these tumor suppressor genes, resulting in promoting cell growth and favoring tumor initiation." (PMID 34298972, 2021).
tumor (continued). "As our analysis shows that only a small fraction of the mutations appears in tumors, we speculate that many MEN1 germline mutations do not drive neoplasia." (PMID 32937789, 2020). "The mutation of the MEN1 gene is often heterozygous mutation, and cell function can be normal; however, once the normal allelic gene develops a deletion, loss of heterozygosity (LOH) will occur, which will lead to the loss of large areas of normal chromosomes and tumor development." (PMID 32126984, 2020). "In addition, MEN1 could act as a tumor suppressor gene by regulating the mTOR signaling pathway (a pathway that has been implicated in cancer progression) to restore CD8+ T cell activity and function." (PMID 31349612, 2019). "The genetic diagnosis of MEN1 is made in a patient who has a germline mutation in the MEN1 gene but may be asymptomatic and has not manifested evidence of tumor presence." (PMID 30459713, 2018). "These tumours have not traditionally been associated with MEN1; however there is increasing evidence that a proportion of them may have a genetic basis." (PMID 28965289, 2017). "However, even in MEN1 patients, these localization studies may distinguish those with multiple large tumors from those with a single tumor." (PMID 27402205, 2016). "Thus, the polymorphism may play a role in dictating the evolution of the malignancy whereby MEN1 acts as a ‘driver’ gene and the CDKN1B polymorphism as a ‘modifier’ of tumour progression." (PMID 25824098, 2015). "Interestingly, the MEN1-associated mutants found to be phosphorylated at Ser394, H139D and A242V, are also the tumor mutants that have been shown to not have the ability to interact with histone methyltransferase activity (HMTase)." (PMID 21264250, 2011). "A subset of MEN1-associated missense point mutants failed to become phosphorylated after DNA damage and may link altered tumor suppressor function to the DNA damage response." (PMID 21264250, 2011). "Another example involves MEN1, which, in physiological conditions, activates lncRNA MEG3, which downregulates c-Met proto-oncogene expression, acting as a tumor suppressor." (PMID 41514582, 2025). "MEN1, which was also previously identified as a leading-edge gene for feedlot beef cattle with BRD, functions as a tumor suppressor." (PMID 40725399, 2025). "In addition, studies in cell lines and animal models have shown that MEN1 mutations lead to an upregulation of the enzyme dihydroorotate dehydrogenase (DHODH), and administration of the DHODH inhibitor, leflunomide, attenuates cell growth and tumor progression." (PMID 38893191, 2024). "The family described herein exhibits classical MEN1 phenotypes, including PHPT in 4 out of 5 carriers, and various neoplasms such as DP-NETs in 2 out of 5 carriers, and PitNENs in 2 out of 5 carriers." (PMID 39104820, 2024). "The anti-tumor effects of HDACis have been further demonstrated in a BON-1 xenograft model and a pancreatic beta cell-specific MEN1 knockout mouse model." (PMID 38279330, 2024). "In pooled differential expression analyses between healthy and tumor samples more proteins were downregulated, while several proliferation-related proteins (e.g., POL2RK, MEN1, MNAT1, TAF9, or SDHC) and biological processes were upregulated." (PMID 38802361, 2024). "This latter group included the presence of MEN1; presence of acid secretory complications; moderate GERD; large tumor size; more advanced disease; or the presence of higher acid control levels." (PMID 36900170, 2023). "While there are zebrafish models for common neuroendocrine tumor genomics, including MEN1, VHL, DAXX, and ACTH, only one model of pNEN tumor development has been published." (PMID 37568572, 2023).
tumor (continued). "Thymectomy in a male MEN1 patient with a smoking history, a thymic NET, and ectopic CS revealed tumor invasion of the right atrium and metastases to the mediastinal lymph nodes- the patient eventually died from metastatic disease." (PMID 37409236, 2023). "Moreover, the variability of menin IHC in MEN1-related tumors may indicate the pattern of tumor formation rather than the diagnostic utility of menin in MEN1." (PMID 37867522, 2023). "We found that in MEN1-derived cells, GLP-1 production was increased and it was also confirmed in the orthotopic tumor of the patient." (PMID 35954231, 2022). "We observed that MEN1 and JunD inhibition with MI503 gave rise to significantly accelerated tumor growth, compared to the control treatment." (PMID 34446068, 2021). "In some MEN1 patients, poorly differentiated PIT1-lineage tumours, previously known as “silent subtype 3 adenoma”, have been observed, with a variable combination of GH, prolactin, α-subunit and thyroid-stimulating hormone." (PMID 33805450, 2021). "Pancreatic neuroendocrine tumours (PNETs) were the most frequent tumour type observed at necropsy and were detected in >85% of 129S6/SvEv and C57BL/6 Men1+/-mice." (PMID 32348957, 2020). "For this reason it is generally recommended that MEN1 screening be performed in all patients with ZES; in particular if the gastrin producing tumour is found in the duodenum." (PMID 28965289, 2017). "Other MEN1-associated endocrine (adrenocortical tumors and carcinoids) and non-endocrine, mostly benign, neoplasms (facial angiofibromas, collagenomas, and others) may also occur, and other types of tumors (e.g. adrenal) are occasionally reported in the literature." (PMID 28184288, 2017). "To further analyze the role of ARC on β-cell tumor load, we assessed the effects of ARC deletion on β-cell proliferation and apoptosis in Pdx1-Cre; Men1 f/f mice." (PMID 26709830, 2015). "Thus, a definite proportion of familial and sporadic MEN1 patients do not carry MEN1 mutations, indicating that other tumor-susceptibility genes may be involved in the pathogenesis of this syndrome." (PMID 25416039, 2015). "Seventeen of 47 patients with genotype-negative disease and available tumor(s) from 1 or more of the 3 primary MEN1-related manifestations were identified." (PMID 39946193, 2025). "The only study that investigated tumors from patients with genotype-negative MEN1 included samples from only 6 patients with a single tumor from each, limiting its broad extrapolation." (PMID 39946193, 2025). "In MEN1 patients with mild disease, the median tumor size in EUS was 1.3 cm (IQR 0.9–2.1 cm), and those patients who were scheduled for an operative procedure (n = 28) presented a median tumor size of 2 cm (IQR 1.4–2.9 cm)." (PMID 40170567, 2025). "A study that evaluated the natural course of microadenomas in a large MEN1 cohort showed that only 9.7% had minimal tumor growth over a follow up period of 5.3 years, none progressing to a macroadenoma." (PMID 40862107, 2025). "In this family, as in the present case, coexistence of MEN1 and RET mutations did not alter tumor onset, behavior or typical phenotype compared to patients with isolated mutations." (PMID 40476723, 2025). "In conclusion, CgA and PP are not helpful in diagnosing panNETs in MEN1, not even in cases where tumor size exceeds 20 mm, the recommended cut-off for surgery." (PMID 40455177, 2025). "A systematic review showed that tumor markers, like chromogranin A, pancreatic polypeptide (PP), or glucagon, are not helpful in diagnosing NF-PanNETs in MEN1 patients due to their low sensitivity and specificity." (PMID 38893191, 2024). "Furthermore, two-hit inactivation of MEN1 and DAXX was observed in NETs with deletions, at a higher frequency than in the other tumor types." (PMID 39456803, 2024).
tumor (continued). "Further on, a connection with glucagonoma was established, regardless of if the neoplasia was a part of MEN1 in some patients (in addition to other endocrine tumors in the pituitary, parathyroid, thyroid, and adrenal glands)." (PMID 39337252, 2024). "A GTE and AFCE (Association Francophone de Chirurgie Endocrinienne) cohort study including 603 patients with MEN1-related dpNETs reported that the presence of ZES, tumor size > 2 cm, and age > 40 years were independently associated with an increased risk of metastases." (PMID 38893191, 2024). "We, therefore, tested if combined inhibition of MEN1 (MI-503 or VTP50469) and EZH2 (EPZ-6438) could result in synergistic effects on tumor transcriptome and growth in vitro and in vivo." (PMID 37460547, 2023). "Nevertheless, novel reports show that MEN1 interacts with histone deacetylases to repress CCAAT enhancer binding protein beta (C/EBPB) expression during TGF-beta signaling, inducing EMT and preventing C/EBPB-mediated tumor suppression." (PMID 37659057, 2023). "Increased activation of CDK5 was shown in patient tissues and in mice with a dox-inducible p25-GFP system found tumor development within 6 months of activation and showed MEN1 heterogeneity that did not affect the increased CDK5 expression." (PMID 37568572, 2023). "The absence of Men1 in the mouse pancreas impairs caerulein-induced pancreas regeneration and accelerates Kras-induced tumor formation." (PMID 36874143, 2023). "In MEN1 mutation‐associated tumors, DHODH expression was enhanced due to the absence of MEN1 protein, leading to massive proliferation of tumor cells." (PMID 36925702, 2023). "Moreover, analysis of RNA-seq data from ICGC expression profiling dataset revealed positive correlation of MEN1 and DOT1L mRNA expression in OC tumours indicating to existence of a subset of OC tumours that expresses both proteins." (PMID 36333801, 2022). "Importantly, MEN1 depletion induced inhibition of activity of MYC proto-oncogene, known to be amplified in around 64% of OC tumours and activated in over half of human cancers including OC." (PMID 36333801, 2022). "Since menin is involved in gene expression control, we then focused our attention on analysis of transcriptome changes induced by MEN1 knock-down in PEO1 and PEO4 cells representing relapsed and chemotherapy-resistant OC tumours and chosen while displaying the highest expression of menin protein." (PMID 36333801, 2022). "In one excised tumor, LOH was identified by all six polymorphic markers spanning the MEN1 locus." (PMID 36325452, 2022). "Some studies have investigated the HRQoL in MEN1 patients by using questionnaires commonly used in other chronic or tumoral diseases, given that there are no dedicated questionnaires, and they have obtained interesting preliminary results." (PMID 33407684, 2021). "In particular, germline and somatic genome alterations (AIP, MEN1, GNAS, and USP8), dysregulated signaling pathways (Notch, Wnt, TGF-β, and cell cycle regulation), and tumor microenvironment factors were characterized, while the role of other species of RNA awaits full characterization." (PMID 33808624, 2021). "What is particularly interesting is that these same pathways and genes are upregulated in metastatic pancreatic neuroendocrine tumors, a tumor type that is presumed to have different tumor drivers than ileal NETs (e.g., MEN1 but not IGF2)." (PMID 34680217, 2021). "Patients with early stage MEN1-related pNENs potentially respond well to “non-aggressive” treatment (such as SSAs) and result in long-term stabilization of tumor growth." (PMID 34681263, 2021). "One limitation of our study is that not all tumor samples showed evidence of LOH at the MEN1 locus, likely because of incomplete separation of tumor and non-tumoral cells." (PMID 34515662, 2021). "These include MEN1, a known WNT pathway tumor suppressor, and WNT16, a WNT ligand that may act as an antagonist of ligand mediated WNT activation." (PMID 32384699, 2020).